SUSD3 (sushi domain containing 3)
Diseases named in the same sentence as SUSD3 in open-access papers (continued):
Sharing a sentence is not in itself a finding about the gene and the disease.
cancer (continued). "However, high levels of SUSD3 expression were not limited to these two cancers; it was also notably elevated in five other cancer types." (PMID 40191190, 2025). "The findings suggest that SUSD3 may influence cancer initiation, prognosis, and therapeutic outcomes through its modulation of immune cell infiltration." (PMID 40191190, 2025). "This suggests that SUSD3 expression may influence cancer prognosis and progression by modulating the TME." (PMID 40191190, 2025). "Spearman correlation analysis between SUSD3 methylation and mRNA expression indicated a strong association between methylation levels and mRNA expression across most cancer types, excluding PCPG and DLBC cancers." (PMID 40191190, 2025). "Subsequently, the cBioPortal database was utilized to investigate whether the SUSD3 gene undergoes alterations at the genomic level across different cancers." (PMID 40191190, 2025). "This insight suggests that incorporating SUSD3 as a biomarker or therapeutic target could open up new possibilities in cancer treatment, particularly in combination with existing MEK1/2 inhibitors and other targeted therapies." (PMID 40191190, 2025). "The promise of SUSD3 as both a predictive biomarker and a target for therapy could offer novel, effective solutions for cancer treatment and prognosis, ultimately improving patient outcomes." (PMID 40191190, 2025). "Targeting TAMs has shown potential for improving prognosis, suggesting that SUSD3 may influence cancer outcomes by modulating TAMs and other immune components." (PMID 40191190, 2025). "Furthermore, subsequent assays revealed a significant decrease in the migratory capacity of cancer cells upon reduction of SUSD3 expression." (PMID 40191190, 2025). "Understanding the precise mechanisms through which SUSD3 interacts with immune and cancer-related pathways could pave the way for novel therapeutic approaches, particularly those aiming to manipulate the immune environment for enhanced cancer treatment outcomes." (PMID 40191190, 2025). "Altered SUSD3 levels could serve as a predictive biomarker for cancer progression." (PMID 40191190, 2025). "Finally, SUSD3 knockdown reduced cancer cell proliferation and migration." (PMID 40191190, 2025). "Subsequently, Spearman correlation analyses between SUSD3 CNV and mRNA expression were performed across multiple cancers." (PMID 40191190, 2025). "The expression levels of SUSD3 in different tissues were assessed using the TIMER database, followed by an exploration of its functional role in cancer, including its interactions and co-expression with other proteins." (PMID 40191190, 2025). "The findings revealed a significant positive correlation between SUSD3 expression and the StromalScore, ImmuneScore, and ESTIMATE scores in multiple cancer types, including BLCA, PAAD, PCPG, and PLAD." (PMID 40191190, 2025). "Each successive layer expresses additional cancer marker genes – considering top-1 markers, coexpression hotspot 0 (CH0) expresses DEGS2; CH2 expresses BRINP3; CH10 expresses SUSD3; and CH19 expresses LOXL2." (PMID 37848426, 2023). "Moreover, spatial transcriptional data obtained from the STOmics DB database revealed a spatial overlap between SUSD3 expression and markers of M2 macrophages, namely CD163 and CD68, within HINSC cancer tissues." (PMID 40191190, 2025). "However, while this study offers valuable insights into SUSD3’s prognostic and predictive potential, the specific molecular mechanisms by which SUSD3 influences cancer progression and therapy response are still not fully understood." (PMID 40191190, 2025).
cardiovascular diseases (1 paper, 2023). "Previous study indicated that SUSD3 may play a role in cardiovascular diseases." (PMID 37203300, 2023).
SUSD3 also shares sentences with these, for which no sentence is quoted: clear cell renal carcinoma (1 paper); coronary heart disease (1); invasive breast carcinoma (1); pan (1); pancreatic cancer (1); primary immunodeficiency (1).